CXCL3 (C-X-C motif chemokine ligand 3)
Diseases named in the same sentence as CXCL3 in open-access papers (continued):
Sharing a sentence is not in itself a finding about the gene and the disease.
cancer (continued). "Overexpression of CXCL Genes: Several CXCL genes (e.g. CXCL1, CXCL3, CXCL8) show significant overexpression, indicating their potential role in promoting tumorigenesis and cancer progression." (PMID 39546375, 2024). "CXCL3 binds to CXCR2, which is expressed in endothelial cells, various immune cells and cancer cells." (PMID 37465363, 2023). "Out of the detected hub genes, six (CCL20, CXCL1, CXCL3, CXCL8, CXCL11, and MMP1) were among over-expressed vDEGs which have been corroborated by the GEPIA in both COAD and READ cancer types." (PMID 35333898, 2022). "Cancer cells expressed high levels of ligands CXCL1, CXCL2, CXCL3, and CXCL8, signaling to the receptors CXCR1 and CXCR2 expressed by neutrophils." (PMID 33953163, 2021). "Combining NPG with HO-1 inhibitor demonstrated down-regulation of genes involved in cancer cell invasion and proliferation (EGR1, CXCL2, AREG, CXCL3, EREG, CD3e, CD3g, CD74, and B2M) as compared to NPG or to control animals." (PMID 34066839, 2021). "miR-561-5p with high expression in HCC directly target to reduce the expression of CXCL3, reduce the infiltration of CXCR3+ NK cell subtypes in TME, promote the survival of cancer cells, and promote lung metastasis." (PMID 33869023, 2021). "In sum, CXCL3, SLC7A5, SLC26A2, GART, and CCDC68 genes were differentially expressed in three or more cancer types." (PMID 29843204, 2019). "In vitro, IL-27 was ineffective on cancer cell proliferation or apoptosis, but fostered CXCL3/GROγ/MIP2β expression." (PMID 25638163, 2015). "Interestingly, interaction with BMMs, however, strongly induced neutrophil recruiting chemokines like Cxcl2, Cxcl3, Cxcl5, and Cxcl15 in classical PDAC cells, whereas release remained unchanged (9091) or increased much less (8513) in mesenchymal cancer cells." (PMID 37156840, 2023). "Taking into consideration the cancer development process, the following histaminergic genes stood out: GNA15, HRH1-HRH4, MAOA, WASF2, along with inflammation-related genes: AEBP1, CXCL1, CXCL2, CXCL3, CXCL8, SPHK1, and TNFAIP6." (PMID 36902343, 2023). "Moreover, the upregulated expression of SOD2, IL1B, PLAUR, CXCL3, and CCL20 promoting cancer cell invasion in other tumors depended on the NF-κB mechanism." (PMID 37954130, 2023). "CXCL3 could bind to the chemokine receptor CXCR2 and regulates the progression and metastasis of malignant tumor." (PMID 32430842, 2020). "Also, the transcriptional expressions of CXCLs family members were correlated with patients' individual cancer stages and nodal metastasis status, especially for CXCL2, CXCL3, CXCL4, CXCL7, CXCL9, CXCL10, CXCL11, and CXCL12." (PMID 32963527, 2020). "Similarly, the pro-angiogenic cytokines such as CXCL1 [chemokine (C-X-C motif) ligand 1], CXCL3, and CXCL6, [chemokine (C-X-C motif) ligand 6], which are typically expressed in highly aggressive cancer, were found to be down-regulated in LNCaP-MST cells." (PMID 29748481, 2018). "Here, we showed that Ikaros may indirectly down-regulate CXCL3 expression in HCC cells, which leads to better outcomes in patients with CD133+ cancer stem cell (CSC) populations." (PMID 27255419, 2016). "But IL1RAP (p = 4.234 × 10−11), CXCL3 (p = 0), CXCL5 (p = 0), and CXCL6 (p = 0) gene expression levels had higher expression in ER-negative than ER-positive ones; whereas IL6ST was the only gene whose expression was higher in ER-positive cancer patients (p = 0)." (PMID 39201290, 2024). "Both the HFD and the cancer cells increased the expression of most genes; however, especially Il1b, Ym1, Cxcl2, Cxcl3, and Cxcr2 were among the most responsive genes to both the HFD and the cancer cells in the PSF which were further exacerbated by the combination of the HFD and cancer cells." (PMID 38264656, 2023).
cancer (continued). "Interestingly, the genes coding for chemokines such as CXCL1, CXCL2, CXCL3, and CXCL8 (IL-8) were strongly upregulated in CD4+ T cells co-cultured with cancer cells only, further suggesting the direct influence of cancer cells on chemokine expression in CD4+ T cells." (PMID 34439305, 2021).
infection (73 papers, 2007 to 2025). The state of being infected such as from the introduction of a foreign agent such as serum, vaccine, antigenic substance or organism. "The gene for the neutrophil-recruiting chemokine CXCL3 was also increased with infection, whereas CCR3, associated with monocyte recruitment, was decreased." (PMID 40682363, 2025). "The decreased Cxcl3 indicated the chemotactic movement of neutrophils can be weakened, resulting in the testis susceptibility to infection." (PMID 38787121, 2024). "At day 3 post-infection, young and aged neutrophils expressed similar levels of Il1b, but young neutrophils expressed higher levels of Il1a; the chemokines Ccl3, Cxcl3, and Cxcl1; and Cd274 (encodes PD-L1)." (PMID 37852965, 2023). "Overexpression of CXCL2, TNFAIP3, ATF3, and CXCL3 increased VEEV-TC-83 infection, suggesting rate limitation associated with these candidate proviral factors." (PMID 33788849, 2021). "On the other hand, it is well established that CXCL8 induces chemotaxis in target cells, primarily neutrophils but also other granulocytes, causing them to migrate toward the site of infection while CXCL3 and CXCL2 controls migration and adhesion of neutrophils and monocytes." (PMID 32182886, 2020). "Indeed, genes within the IL-17 pathway including Cebpb, Tnf, IL-6, Cxcl1, Cxcl2, Cxcl3, Cxcl5, Cxcl10, and Ccl7 were shown to be up-regulated in both susceptible and resistant mice during infection." (PMID 29339782, 2018). "Expression of the ligands Spp1, Cxcl2, and Cxcl3 were abundant in keratinocytes, fibroblasts, and M2-like macrophages during the infection." (PMID 38767331, 2024). "Cxcl1 and Cxcl5 production were induced in epithelial cells following chronic H. felis infection, while Cxcl2 and Cxcl3 production was induced in epithelial, myeloid, and T cell subsets following infection." (PMID 37744359, 2023). "CXCL3 transcription increased rapidly 1 h post infection, especially in the U251 cells; transcription in these cells, was considerably higher than that in hBMECs." (PMID 37445610, 2023). "Some up-regulated genes at 21 dpi (e.g., Ltf, Cxcl9, Pglyrp1, Prg2, Cxcl13, Cxcl3, Ccl9, Ccl19, Krt5, Krt14, Krt15, Krt17, and Slpi) were also identified in a previous infection study by using H1N1(PR8)." (PMID 38005876, 2023). "Typical inflammatory chemokines, including Ccl4, Ccl3, Cxcl2, Cxcl3, and Cxcr2, induces immune cells to enter the site of infection during the immune response." (PMID 37580334, 2023). "High CXCL3 levels have been detected in mouse brain tissue after infection, and CXCL3 interacts with CXCR2 (the receptor) to produce a range of biological effects." (PMID 37445610, 2023). "VSV infection significantly induced the expression of seven chemokines (CCL3, CCL4, CCL5, CCL20, CXCL1, CXCL2, and CXCL3) by ~3- to 42-fold compared to mock infection." (PMID 34578166, 2021). "We noted a strong upregulation of genes encoding for CXCL2, CXCL3, CXCL10, IFNβ-1, IFNλ-1, -2, -3, endothelin 1 (EDN1) and IFIT-1, -2, -3 following E-30 infection." (PMID 32872518, 2020). "At 2 h post infection (p.i.), enhanced accumulation of mRNAs for Cxcl1, Cxcl2, Cxcl3, and Cxcl5, as well as Ccl3 and Ccl4, was evident (determined as differentially expressed using a 5% FDR)." (PMID 29636754, 2018). "A few mRNAs of immunological interest, namely Lyz1, S100a11, and Cxcl3 exhibited elevated ribosome occupancy in all infection conditions." (PMID 28383283, 2017). "This is consistent with previously published results showing the expression pattern of CXCL3 during infection of the SJL/J mouse strain that is resistant to a moderately virulent strain of C. neoformans (strain 24067)." (PMID 27165801, 2016). "The infection also activates the transcription of Cxcl1, Cxcl2 that regulate the influx of PMNs, Cxcl3 that controls migration of monocytes, Cxcl9 the Th1-attracting protein and the interferon-γ - inducible protein-10 (IP-10/Ccxl10)." (PMID 24148319, 2013).
infection (continued). "Interestingly, a similar increase was also seen after mock infection with heat-inactivated virus, but generally only at 3 and 6 hr (e.g., CXCL3 and IL6)." (PMID 39869630, 2025). "Various chemokines (small proteins that guide white blood cells to sites of infection, injury, or inflammation) in this pathway, such as Cxcl1, Cxcl2, Cxcl3, and Cxcl5 and Ccl20, showed significant differences in expression levels between the LV149-L and the DSS group." (PMID 39845056, 2024). "Furthermore, Cxcl3 (FC = 41.4) and the antimicrobial proteins S100a9, S100a8 (FC = 204.3 and 90.7), and Ccl3l1 (FC = 28.5) were strongly upregulated by infection." (PMID 38251349, 2023). "Similarly, Cxcl2 and Cxcl3 expression were increased during infection; however, there was a significant defect in TRPV1-/- mice to express these chemokines 29 days p.i. compared to WT mice." (PMID 38109366, 2023). "Furthermore, serum CXCL3 expression increased 2 h post infection and continued increasing time-dependently." (PMID 37445610, 2023). "Activation of these transcription factors may lead to expression of various cytokines genes such as IL1B, CXCL2 and CXCL3, which in turn recruits immune cells to the site of infection." (PMID 37193047, 2022). "The up-regulated CXCL3 were recognized in early infection models of SARS-CoV-2." (PMID 36016187, 2022). "In the case of CINCs, it is not expressed in the microglia at rest, and LPS strongly induces its release, suggesting that CXCL3 may act as a proinflammatory factor in activated microglia by insults (e.g., infection, injury, stress)." (PMID 31616413, 2019). "The rate of migration of sensory and motor Fbs was suppressed by CXCL10- or CXCL3-siRNA infection." (PMID 30686982, 2018). "Indeed, transcription of CXCL1 (up to 3 fold increase), CXCL2 (up to 3.9 fold) and CXCL3 (up to 2 fold) (alias respectively GROα, GROβ, GROγ) was rapidly induced and persisted during the first 12 hours of infection." (PMID 22928052, 2012). "This conclusion is supported, at least in part, by the results of Sukumaran and colleagues, who reported the upregulated expression of chemokine genes encoding CXCL1, CXCL2, CXCL3, CXCL8, CCL3, CCL4 and CCL20 after infection of PMN with Anaplasma phagocytophilum." (PMID 17875202, 2007). "However, the migration rate of sensory and motor Fbs was suppressed by CXCL3-siRNA infection." (PMID 30686982, 2018). "Consistent with clinical observations, in vitro infection of RD cells and in vivo infection of suckling mice in our study similarly demonstrated significant upregulation of IL-6, TNF-α, CXCL2, CXCL3, CXCL8 (IL-8), and CXCL10." (PMID 40872743, 2025). "Previous studies have shown that BPD-induced damage enhances the function of chemokines and their receptors (e.g., CXCL3, CCR1, CCR2, CCR5), which direct immune cells to sites of infection or injury." (PMID 41345109, 2025). "Similar to 12 h, genes significantly upregulated in the later stages of infection were cytokines or chemokines, such as CXCL1, CXCL2, CXCL3, CXCL8, CXCL10, and CCL20." (PMID 37211158, 2023). "The early infection models of SARS-CoV-2 demonstrated upregulated pro-viral factors such as TYMP, PTGS2, C1S, CFB, IFI44, XAF1, CXCL2, and CXCL3." (PMID 36016187, 2022). "The proinflammatory chemokines CCL3, CXCL3, and CXCL10 were also upregulated following infection, while synapse-related genes, including C1QL1 and SYPL1, were downregulated." (PMID 36314791, 2022). "A more detailed analysis of DEGs indicated on a strong immune response in MKN-28 cells after 2-h infection based on increased transcription of IL1A, IL8, IL24, CXCL2, CXCL3 and CCL20." (PMID 37193047, 2022). "ELR-type chemokines activated by cp strain infection included CXCL1, CXCL3, CXCL5, CXCL8, and CXCL15." (PMID 35746747, 2022). "The modules that were co-up-regulated in CD4 and CD8 cells after infection included IRF9, IRF7, PLCB3, CXCL3, and TXN, among others." (PMID 34603402, 2021).
infection (continued). "The chemokines CXCL2, CXCL3 and CXCL10 are part of “the immune response” pathway, which is highly upregulated following basolateral infection compared to control, as shown in the gene set enrichment analysis (GSEA)." (PMID 32872518, 2020). "Here, both basolateral and apical infection led to the upregulation of CXCL2 and CXCL3 in HIBCPP cells." (PMID 32872518, 2020). "We found upregulated genes that were also upregulated following basolateral infection, such as CXCL2, CXCL3, CXCL10, IFNβ-1, IFNλ-1, -2, -3, endothelin 1 (EDN1) and IFIT-1, -2 and -3." (PMID 32872518, 2020). "We found a decreased expression of GRO1, CXCL2, CXCL3, and IL1A; these are all important genes for innate immunity during pathogen infection." (PMID 33374309, 2020). "The genes, Ccl2, Ccl20, Csf1, Cx3cl1, Cxcl1, Cxcl3, Il6, Birc3, Map3k8, Nos2, Nfkb2, Tnfrsf1b, and Vcam1, played core roles in a PPI network, and interacted closely with other ones in the infection." (PMID 33042984, 2020). "A previous study has shown that basolateral infection of HIBCPP cells with E-30 resulted in an increased expression of CXCL2 and CXCL3, two chemokines that play a role during inflammation processes." (PMID 32872518, 2020). "We verified a strong upregulation of CXCL2, CXCL3, IFNλ-1, -2 and IFIT-2 genes following a basolateral infection of HIBCPP with E-30 at MOI 0.7 compared to uninfected conditions." (PMID 32872518, 2020). "Similar to CXCL10, the proliferation rate of sensory Fbs (10K) was significantly suppressed by CXCL3-siRNA infection, while the proliferation rate of motor Fbs (10K) was enhanced by CXCL 3-siRNA infection." (PMID 30686982, 2018). "This unique chemokine profile targets different populations of immune cells like dendritic cells, T cells, and B cells by CCL20, neutrophils by CXCL1 to CXCL3, and macrophages and T-cells by CCL2 to the site of infection." (PMID 29726306, 2018). "A time dependent upregulation of CXCL1, CXCL2, CXCL3, IL-8, and CCL5 after infection with EV30 was observed." (PMID 27313404, 2016). "We also saw statistically significant upregulation in the level of CXCL3, a CXCL-1–type chemokine that is important for attracting neutrophils to the site of infection, in the lungs of mice infected with 107 CFU of the cda1Δ2Δ3Δ mutant." (PMID 27165801, 2016). "The list of genes with the greatest induction following Mtb:Δ-sigH infection at this time-point included CXCL1 (120-fold), PTGS2 (100-fold), CXCL6 (75-fold), CCL2 (53-fold), CXCL3 (40-fold), CXCL1 (43-fold) and CCL2 (38-fold) CCL5 (35-fold)." (PMID 22235255, 2012). "Additionally, chemokine-encoding genes involved in the recruitment of immune cells such as CXCL2, CXCL3 and CCL20 were upregulated during the course of infection." (PMID 40794782, 2025). "On the other hand, parts of the tissue with resolved infection did not display expression of pro-inflammatory cytokines such as Cxcl3." (PMID 40586608, 2025). "Therefore, to assess the role of CXCL1, CXCL2, CXCL3, and CXCL5 in neutrophil trafficking during infection with C. violaceum, we used a CXCR2 inhibitor." (PMID 38352492, 2024). "Our previous study found that infection with meningitic E. coli can significantly increase the expression of chemokines and cytokines, such as IL-6, IL-1β, TNF-α, CXCL3, CXCL2, and C-C motif chemokine ligand (CCL) 2, and some chemokines remain at high levels in the blood and brain for a long time." (PMID 37445610, 2023). "Furthermore, we verified the upregulation of CXCL8, CXCL2, CXCL3, IFNλ-1, -2 and IFIT-2 genes following an apical infection of HIBCPP cells with E-30 at MOI 20 compared to uninfected condition." (PMID 32872518, 2020). "Among them, Cxcl1, Cxcl2, Cxcl3, Cxcl10, IL1b, Socs3, and Mmp14 were overexpressed more than 100-fold compared with the non-infected sample regardless of infection type." (PMID 30858471, 2019). "While not significantly upregulated following infection, transcription of ATF3, CXCL3, CXCL8, and PTGS2 was at least partially dependent on EGR1." (PMID 35746681, 2022).
infection (continued). "The expression of CXCL3, CXCL5, and CXCL9 during A. baumannii infection has not previously been quantified, and the role that these effectors play in the outcome of infection is unknown." (PMID 36054235, 2022).
cardiovascular diseases (3 papers, 2019 to 2025). "Many hot nodes in the PPI network are inflammatory factors, including IL8, IL1B, CXCL3, CXCL12, and HLA genes, which are associated with cardiovascular diseases." (PMID 30885136, 2019).
colon polyps (2 papers, 2023 to 2024). "Validation by qRT-PCR confirmed increased expression of the LCN2, IL1B, CXCL1, and CXCL3 genes in CCS colonic polyps." (PMID 38297356, 2024).
colorectal (2 papers, 2015 to 2017). "The LMP7-dependent up-regulation of CXCL1, CXCL2, CXCL3 and VCAM-1 expression leads to alternations in the microenvironment of tumors and progression of colorectal carcinogenesis." (PMID 28881574, 2017).
immune diseases (2 papers, 2021 to 2022). "CXCL3 levels are elevated in many tumors and immune diseases, although there are no reports of CXCL3 expression in CRC." (PMID 35664357, 2022).
inflammation (1 paper, 2021). Aberrant reaction of the microcirculation characterized by movement of fluid and leukocytes from the blood into extravascular tissues. "Taken together, the current transcriptomic findings revealed anti-UC pharmacological targets, including the newly discovered biotargets CCL11, CCL21, CXCL3, and CXCR2, of mesalazine against DSS-induced intestinal inflammation." (PMID 34456974, 2021).
CXCL3 also shares sentences with these, for which no sentence is quoted: pancreatic adenocarcinoma (4 papers); adenocarcinoma (3); bacterial infections (3); gastritis (2); lung diseases (2); neuroblastoma (2); peripheral nerve injury (2); pneumonia (2); renal cell carcinoma (2); systemic lupus erythematosus (2); ulcerative colitis (2); acute coronary syndrome (1); airway hyperresponsiveness (1); alcoholic hepatitis (1); amoebiasis (1); astrocytoma (1); bladder cancer (1); bronchitis (1); Carcinoid (1); cholangiocarcinoma (1); choroid plexus papilloma (1); chronic myeloid leukemia (1); CNS tumor (1); concussion (1); dengue (1); depression (1); diffuse large B-cell lymphoma (1); emphysema (1); encephalitis (1); endocervical adenocarcinoma (1).
A further 34 diseases each share a sentence with CXCL3 in 1 paper.